PKD2 (polycystin 2, transient receptor potential cation channel)
Diseases named in the same sentence as PKD2 in open-access papers (continued):
Sharing a sentence is not in itself a finding about the gene and the disease.
Renal cyst (91 papers, 2007 to 2026). A fluid filled sac in the kidney. "Two other mutations, PKD1 and PKD2, are associated with CKD and cystic kidney disease, respectively, and map to polycystin 1 and polycystin 2, respectively." (PMID 41511357, 2026). "Homozygous mutants were embryonic lethal, whereas heterozygous mice expressing both variant and conditional Pkd2 repression alleles developed pronounced renal cysts." (PMID 41212053, 2025). "Because hepatocyte nuclear factor-1β directly controls PKD2 transcription, the cystic kidney disease seen in patients with HNF1B variants mirrors ADPKD." (PMID 39291187, 2024). "The loss of function of either PKD1 or PKD2 is sufficient to induce autosomal dominant polycystic kidney disease whereby affected individuals develop large and numerous renal cysts leading to renal failure." (PMID 33459801, 2021). "The years 1995 and 1996 marked the discovery of Polycystin 1 (PKD1) and Polycystin 1 (PKD2) as the first genes to be associated with cystic kidney disease through positional cloning." (PMID 34828368, 2021). "Using a mouse model of cystic kidney disease caused by Pkd2 loss, we observe JNK activation in cystic kidneys and observe increased nuclear phospho c-Jun in cystic epithelium." (PMID 34962918, 2021). "Mutations in the PKD1 and PKD2 genes, encoding the polycystin 1 and polycystin 2 Ca2+ ion channels, respectively, result in tubular epithelial cell-derived renal cysts." (PMID 28993480, 2017). "Consistent with a two-hit mechanism, mice that are homozygous for inactivating mutations of either Pkd1 or Pkd2 develop cystic kidneys, edema and hemorrhage and typically die in midgestation." (PMID 20862291, 2010). "Pkd1 and Pkd2 heterozygous mice present with few if any renal cysts but develop dramatic cystic disease when the other allele undergoes somatic deletion at a high rate." (PMID 20862291, 2010). "Although the phenomenology of PKD1 and PKD2 mutations is identical, PKD2 patients experience less severe disease, a less early development of hypertension and atherosclerosis, and probably fewer renal cysts compared to PKD1 patients." (PMID 40362206, 2025). "There is emerging evidence that rare, predicted damaging variants within cystic kidney disease genes such as PKD2, HNF1B and PKHD1 may have a phenotype modifying role." (PMID 39883360, 2025). "To test the hypothesis that altering the pore domain of polycystin-2 is sufficient to cause renal cyst formation, we have created a Pkd2 knock-in mouse model, Pkd2poreL1, in which the mutated polycystin-2 protein contains the pore region of polycystin-2L1." (PMID 34345895, 2021). "In addition to the association seen with PKD1, we also saw a significant association between the related gene PKD2 and cystic kidney disease (CKD)." (PMID 34385667, 2021). "However, these mice rarely develop renal cysts, presumably because 5 months is insufficient time to accumulate spontaneous mutations that inactivate the intact copy of Pkd2 in the kidneys." (PMID 27081851, 2016). "For example, mutations in Pkd1 cause a more severe cystic kidney phenotype than mutations in Pkd2." (PMID 25464512, 2014). "In addition, in humans, ADPKD is a heterozygous state, whereby mutations leading to loss of one PKD1 or PKD2 allele is combined with somatic mutations in the kidney (i.e., a second hit) to cause renal cystic disease." (PMID 23029375, 2012). "Histology was performed after 6–7 months of life where hepatic, lateral, and bilateral renal cysts were present in several individuals within the Pkd2+/R652X cohort, but fewer were observed in Pkd2+/R801X strain." (PMID 41212053, 2025). "The occurrence of renal cysts in patients with COL4A3-COL4A5 variants, independently of PKD1 or PKD2 alterations, underscores the broader implications of collagen IV defects in cystogenesis." (PMID 40565535, 2025). "Remarkably, we observed overall agreement in pre-cystic kidneys even between Pkd2 and Pkd1 models and juvenile and mature mice." (PMID 39666736, 2024).
Renal cyst (continued). "In certain genetic human cystic kidney diseases, such as autosomal dominant PKD (ADPKD) associated with PKD1 or PKD2 mutations, in vivo kidney cystogenesis is largely driven by cAMP signaling." (PMID 38788724, 2024). "In contrast, CD206+ macrophage accumulation was evident around cystic areas at 12 wpi in Pkd2 mutant kidneys and was much more frequent in severe cystic kidneys at 16 wpi." (PMID 36457161, 2023). "In agreement with the reprogramming results in mammalian cells, we detected particularly high induction of genes related to cystic kidney disease, such as bicc and pkd2." (PMID 36522156, 2023). "RNA-seq has identified a kidney-specific, evolutionarily conversed lncRNA called Hoxb3os that was highly expressed in renal tubules in adult wild-type mice but down-regulated in cystic kidneys from Pkd1 and Pkd2 mutant mice." (PMID 36203940, 2022). "Pkd1, Pkd2 and Lgr4, genes involved in cystic kidney disease are now also known to play a role in Wolffian duct coiling." (PMID 35735916, 2022). "At low concentrations of tubacin (0.2 μM), renal cyst size was markedly reduced in PKD2-/- organoids as compared to the control." (PMID 34250905, 2021). "When given chronically, this same antagonist reduced renal cyst formation in Pkd2–/–, as evidenced by reduced kidney weight, BUN, and the cystic index, when compared with untreated mice." (PMID 33886508, 2021). "Differentiation of these PKD1 or PKD2 mutant hPSCs into kidney organoids led to formation of large renal cysts instead of the tubular nephron-like structures." (PMID 33459801, 2021). "In this study, we provide evidence that impaired GTB can occur before renal cystic formed and increased the tubule sensitive to flow by a DA1 antagonist, slowing the renal cyst formation in Pkd2 KO mice." (PMID 33886508, 2021). "Most molecular studies on cystogenesis have focused on ADPKD causing mutations in Pkd1 and Pkd2 genes (encoding PC1 and PC2, respectively) due to their epidemiological burden in comparison with other genes associated with renal cysts." (PMID 34828368, 2021). "By using chromosome conformation capture carbon copy (5C) technology in primary human renal cyst epithelial cells, we identify novel contacts of the PKD2 promoter with chromatin regions, which display characteristics of regulatory elements." (PMID 29986647, 2018). "A case with separate TSC1 and PKD2 mutations had a very modest cystic phenotype, probably due to the relatively mild disease in PKD2 compared to PKD1 and because TSC1 mutations are rarely associated with renal cysts." (PMID 26077033, 2015). "Patients harboring heterozygous germline mutations in PRKCSH are thought to develop renal cysts as a result of somatic loss of the second allele, which subsequently interferes with expression of the TRP channel polycystin-2 (PKD2)." (PMID 26671672, 2015). "Additional supporting evidence implicating Kif12 as the Mpkd2 modifier gene candidate is provided by recent studies that demonstrate renal cystic disease-attenuating effects of Kif3a deletion in Pkd1 and Pkd2 mouse models." (PMID 26295839, 2015). "While ADPKD is predominantly associated with PKD1 and PKD2 gene variants, there are documented cases where individuals with pathogenic variants in COL4A3, COL4A4, or COL4A5 also present with renal cysts and even a clinical diagnosis of polycystic kidney disease (PKD)." (PMID 40565535, 2025). "In addition to regulating mitochondrial OXPHOS/FAO functions, ERRγ also cooperates with HNF1β to activate the expression of renal reabsorption genes including PKD2; deletion of ERRγ in renal tubular epithelial cells results in renal cysts." (PMID 39000280, 2024). "Homozygous mutants of mouse Pkd2 die at embryonic day 13.5, exhibiting defects in the atrioventricular septum, renal cysts, and pancreatic cysts, while heterozygotes show milder pancreatic cysts, suggesting a dosage-dependent regulation of tissue function in mouse kidneys by PKD2." (PMID 39451240, 2024).
Renal cyst (continued). "In addition, to see how Tacstd2 responds in more highly cystic kidneys, we examined P21 tissue collected from another study where Pkd2 was deleted in the early post-natal period by tamoxifen treatment of mothers nursing Rosa26-CreERT2, Pkd2flox/flox pups." (PMID 39666736, 2024). "Furthermore, reports indicate that PKD2 is overexpressed in human renal cyst tissues and can induce renal cysts in mice when overexpressed under model human PKD2 conditions." (PMID 39451240, 2024). "Cystic renal disease is most often ascribed within the heterogeneous group of chronic kidney diseases to ADPKD, which is determined by heterozygous pathogenic variants in PKD1 and PKD2 in the majority of patients." (PMID 38790225, 2024). "Although Pkd1 and Pkd2 are direct miR-17-5p targets, miR-17-5p upregulated by c-Myc was also able to enhance proliferation in cystic kidneys from Pkd1 knockout (KO) ADPKD models, at least in part, by inhibiting mitochondrial oxidative phosphorylation through repressing Pparα." (PMID 36203940, 2022). "Effect of dopamine receptor antagonist on renal cyst formation in Pkd2-KO mice." (PMID 33886508, 2021). "miR-21 is also upregulated in cystic kidneys from Pkd1 conditional knockout mice (Pkd1flox/flox:Pkhd1-Cre mice), Pkd2 conditional knockout mice (Pkd2flox/flox:Pkhd1-Cre mice), and HNF1B conditional knockout mice (Hnf-1βflox/flox:Pkhd1-Cre mice), and in human ADPKD kidneys." (PMID 33809516, 2021). "We observed no morphological changes of the kidneys from the Pkd1-, Pkd2-, and the Kif3a-KO mice 2 weeks after the induction (at the age of 8 weeks) and observed some dilated kidney tubules after 5 weeks of induction; renal cysts developed from 8 weeks of induction in Pkd1 and Pkd2 KO mice." (PMID 33886508, 2021). "JNK signaling promotes interstitial fibrosis in non-cystic kidney disease models As fibrosis also contributes to advanced cystic kidney disease, we hypothesized that Jnk deletion may reduce fibrosis in Pkd2 mutants." (PMID 34962918, 2021). "Although renal cyst formation and kidney failure are arguably the most well-known symptoms of PC2 dysfunction, multiple extrarenal pathologies are also known to occur in patients with loss-of-function PKD2 mutations." (PMID 31941974, 2020). "In tests of these hypotheses, both PKD1 and PKD2 transgenic rodent models exhibited renal cysts and other organ abnormalities." (PMID 31979107, 2020). "Given the role of HNF1β as a master regulator of a number of cystic kidney disease genes including PKHD1 and PKD2, there is a credible genetic cause which might explain the resemblance between HNF1β and ARPKD/ADPKD patients." (PMID 29479522, 2017). "Indeed we found that administration of desmopressin aggravated the renal cystic disease of Pkd2-/WS25 mice on a Pde3a null background compared desmopressin-treated Pkd2-/WS25 mice on a wild-type background." (PMID 28750036, 2017). "The direct comparison of PKD1 and PKD2 patients as well as patients with other cystic renal diseases may allow the identification of genotype-specific markers that might be more closely linked to early disease-initiating processes." (PMID 23326375, 2013). "In comparison, SKAT-O identified only PKD1 and PKD2 after p-value adjustment, whereas PERADIGM identified an additional candidate gene, IFT140 is a well-established gene in ciliopathies that has recently been implicated as a monogenic cause of renal cyst formation." (PMID 41411243, 2025). "Renal ciliopathies are also associated with cystic kidney disease phenotypes, highlighted by autosomal dominant polycystic kidney disease (ADPKD), associated with pathological variants in polycystin-1 (PC1, encoded by PKD1) and polycystin-2 (PC2, encoded by PKD2)." (PMID 41140281, 2025). "Interestingly, the study showed that cilia integrity contributes to renal cyst formation caused by PKD2 deficiency, although the mechanism of this is not clear." (PMID 39451240, 2024).
Renal cyst (continued). "Since the Pkd2 and Pkd2poreL1 genes are prominently expressed in collecting ducts we determined their luminal width in order to test our hypothesis that a polycystin-2 protein with altered ion channel properties leads to a larger tubular diameter (and eventually to renal cysts)." (PMID 34345895, 2021). "Importantly, we observed extensive RGLS4326 uptake in both proximal tubules and collecting duct cysts in cystic kidneys of the aggressive Pkhd1/cre;Pkd2F/F (Pkd2-KO) mouse model of ADPKD following SC administration, likely linked to the severely disrupted kidney architecture in this mouse model." (PMID 31515477, 2019). "Consequently, when a variant is identified in a collagen gene in a patient with cystic kidney features, a comprehensive evaluation for concurrent variants in PKD1, PKD2, or other cystic kidney disease-associated genes might not be routinely performed." (PMID 40565535, 2025). "Enhanced nuclear localization of ID2 has been observed in human and mouse renal cysts, suggesting that ID2 plays a pivotal role in PKD2-mediated cell cycle regulation." (PMID 39451240, 2024). "The protein products of PKD1 and PKD2 are transmembrane proteins called polycystin-1 (TRPP1, PC1) and polycystin-2 (TRPP2, PC2), respectively, whose localization to primary cilia was an essential clue in directly linking primary cilia to renal cysts." (PMID 36267587, 2022). "Consistently, ribozymes that specifically inhibit VEGFR1 and VEGFR2 mRNA expression significantly reduced renal cyst growth in Cy/+ rats, while SU5416, a small-molecule inhibitor of VEGFR2, reduced hepatic cyst growth in Pkd2 KO mice." (PMID 34650051, 2021). "Here we show that Pkd2 deletion increases JNK activation, which contributes to cystic kidneys in young animals and cystic liver in older animals." (PMID 34962918, 2021). "A cystic kidney disease panel should include adequate coverage of PKD1, PKD2, PKHD1, Daz-interacting zinc-finger protein 1-like (DZIP1L), HNF1B and genes for other ciliopathies such as nephronophthisis (NPHP) and Bardet–Biedl syndrome (BBS)." (PMID 31118499, 2019). "Currently, it is recommended that genetic studies be extended in patients with bilateral renal cysts who do not have variations in PKD1 or PKD2 to avoid misdiagnosis." (PMID 40565535, 2025). "In the context of translational research, the observation of renal cysts in human patients with collagen IV gene variations, even without concurrent PKD1 or PKD2 variations, has opened new avenues for understanding the pathogenesis of renal cystic diseases." (PMID 40565535, 2025). "The presence of these renal cysts does not affect the renal function, or cause end-stage renal disease, as seen in PKD1- and PKD2-caused ADPKD." (PMID 37628703, 2023). "Our experimental data show that applications of a DA1 antagonist at the precystic stage prevented renal cyst formation only in Pkd2–/–, which had impaired GTB, but not in Pkd1–/–, which had intact GTB." (PMID 33886508, 2021). "Previously, we failed to observe any renal cysts in a transgenic porcine model of PKD2 overexpression partially due to epigenetic silencing of the transgene." (PMID 31979107, 2020). "Unlike pkd2 mutants, pkd2 morphants develop cystic kidneys, although this appears to be restricted to the glomerulus and proximal tubules rather than the entire pronephros like in other cystic cilia mutants." (PMID 31919453, 2020). "None of the unsolved patients had have family history of kidney disease, therefore mutations in autosomal recessive genes that lead to ARPKD-like phenotypes such as the DZIP1L or even in dominant cystic kidney disease genes such as HNF1B, PKD1 and PKD2 that often occur de novo are possible." (PMID 32799815, 2020). "Comparative differential expression analysis showed a clear trend in global transcriptomic profiles where the expressions of dysregulated genes in the Pkd2-KO and Pcy/CD1 cystic kidneys were improved after RGLS4326 treatment (rho = −0.559 and −0.812, respectively) (y-axis)." (PMID 31515477, 2019).
Renal cyst (continued). "We demonstrate that Pkd2+/- mice have cardiac abnormalities that become more pronounced with aging and mimic the human cardiac defects that arise independent of renal cyst development." (PMID 27081851, 2016). "The lack of renal cysts in the Pkd2 +/- mouse model was expected, as the kidneys still have one intact copy of the Pkd2 gene." (PMID 27081851, 2016). "None of the 9 mo Pkd2 +/- mice examined had renal cysts, and there was no obvious dilation of the tubules in the kidney of the 9 mo Pkd2+/-." (PMID 27081851, 2016). "Because of parental history of bilateral renal cysts, PKD1 and PKD2, genetic testing was ordered." (PMID 26501044, 2015). "Moreover, the number of renal cysts is different in PKD1 and PKD2 patients." (PMID 40362206, 2025). "In addition to somatic mosaicism, PKD2 (n = 5) and PKD1 non-truncating (n = 3) mutations, which are typically associated with mild cystic kidney disease, were found in 8 of 9 (88.9%) mutation-positive patients with atypical imaging patterns in our study." (PMID 36807559, 2023). "Furthermore, considering the clinical similarity of ADPKD with other kidney cystic diseases, causing incorrect clinical diagnosis in the absence of familial history, molecular study for PKD1 with or without PKD2 in suspected patients is recommended." (PMID 32957937, 2020). "Thus, our data suggest that the Pkd2+/- mice lose cardiac function in the absence of renal cysts, pointing to a cardiac specific function of PC2." (PMID 27081851, 2016). "However, among patients with no family history (the 10–25% who have no parent with ADPKD), some 40% reportedly have no observed mutation in the PKD1 or PKD2 genes; this suggests that careful diagnosis is required to differentiate between ADPKD and other cystic kidney diseases." (PMID 36362756, 2022). "Given that the heterozygous PKD2 mouse model does not induce renal cysts, we hypothesize that depletion of 11β-HSD expression may require the heterozygosity of PKD2 to induce renal cystogenesis, mimicking the third-hit model." (PMID 39085216, 2024).